CHCHD4 (coiled-coil-helix-coiled-coil-helix domain containing 4)
Description:
Central component of a redox-sensitive mitochondrial intermembrane space import machinery which is required for the biogenesis of respiratory chain complexes. Functions as a chaperone and catalyzes the formation of disulfide bonds in substrate proteins, such as COA7, COX17, COX19, MICU1 and TIMCC/FAM136A. Required for the import and folding of small cysteine-containing proteins (small Tim) in the mitochondrial intermembrane space (IMS). Required for the import of COA7 in the IMS. Precursor proteins to be imported into the IMS are translocated in their reduced form into the mitochondria. The oxidized form of CHCHD4/MIA40 forms a transient intermolecular disulfide bridge with the reduced precursor protein, resulting in oxidation of the precursor protein that now contains an intramolecular disulfide bond and is able to undergo folding in the IMS. Reduced CHCHD4/MIA40 is then reoxidized by GFER/ERV1 via a disulfide relay system. Mediates formation of disulfide bond in MICU1 in the IMS, promoting formation of the MICU1-MICU2 heterodimer that regulates mitochondrial calcium uptake.
Synonyms: MIA40; FLJ31709; TIMM40
Tractability: Small molecule: a structure with a bound ligand is known. PROTAC: ubiquitination databases record sites on it.
Gene: Protein-coding gene on chromosome 3 (14,112,077 to 14,124,876, reverse strand). Ensembl gene ENSG00000163528.
Subcellular location: Mitochondrion intermembrane space
Subcellular location (Human Protein Atlas): Mitochondria
Pathways (Reactome):
Protein localization: Mitochondrial protein import
Gene Ontology:
Molecular function: protein binding; protein-disulfide reductase activity
Biological process: mitochondrial disulfide relay system; mitochondrial respiratory chain complex assembly; protein import into mitochondrial intermembrane space; protein maturation
Cellular component: mitochondrial intermembrane space; mitochondrion
Genetic constraint (gnomAD): Loss-of-function variants: 6 observed, 9.66 expected, observed/expected ratio (o/e) 0.62, 90% interval 0.34 to 1.23. That is too few expected variants to judge how well the gene tolerates losing a copy. Missense variants: 128 observed, 160.03 expected, observed/expected ratio (o/e) 0.8, 90% interval 0.69 to 0.93. Synonymous variants: 48 observed, 53.02 expected, observed/expected ratio (o/e) 0.91, 90% interval 0.72 to 1.15.
Homologues: Orthologues: chimpanzee CHCHD4 (96% identical), guinea pig CHCHD4 (89% identical), pig CHCHD4 (88% identical), dog CHCHD4 (87% identical), rat Chchd4 (87% identical), mouse Chchd4 (86% identical), rabbit CHCHD4 (85% identical), rat Chchd4-ps1 (82% identical), tropical clawed frog chchd4 (81% identical), rat LOC120094797 (80% identical), rat Chchd4l1 (70% identical), zebrafish chchd4a (70% identical), and 5 more.
Diseases named in the same sentence as CHCHD4 in open-access papers:
CHCHD4 is named in the same sentence as 25 diseases in open-access papers, as found by Europe PMC text mining. Sharing a sentence is not in itself a finding about the gene and the disease. The quoted sentences say what the papers report.
lung adenocarcinoma (3 papers, 2022 to 2023). A carcinoma that arises from the lung and is characterized by the presence of malignant glandular epithelial cells. "Recent studies have shown strong correlation of CHCHD4 with poor prognosis in lung adenocarcinoma and development of tumor cell growth." (PMID 37438854, 2023). "This study aimed to identify genes related to lung adenocarcinoma (LUAD) and investigate the effects and molecular mechanisms of coiled-coil-helix-coiled-coil-helix domain containing 4 (CHCHD4) in the progression of LUAD." (PMID 36482116, 2022).
glioma (2 papers, 2017 to 2021). A benign or malignant brain and spinal cord tumor that arises from glial cells (astrocytes, oligodendrocytes, ependymal cells). "We discovered previously that increased expression of CHCHD4 in human cancers (e.g., breast, glioma, and pancreatic) is associated with the upregulation of hypoxia regulated genes and poor patient survival." (PMID 28497026, 2017).
renal carcinoma (2 papers, 2018 to 2019). A carcinoma arising from the epithelium of the renal parenchyma or the renal pelvis. "Our study reveals a new role for pVHL in regulating CHCHD4 and mitochondrial function in renal carcinoma cells." (PMID 30338240, 2018). "We show that pVHL increases the expression of CHCHD4, respiratory chain subunits known to be CHCHD4 substrates and promotes changes in mitochondrial morphology when re-expressed in pVHL-defective renal carcinoma cells." (PMID 30338240, 2018). "Depletion of CHCHD4 using two independent siRNAs similarly reduced the expression of these respiratory chain subunits, as we have also shown in our recent study using renal carcinoma cells." (PMID 30886710, 2019). "Thus, investigating the importance of CHCHD4 expression levels in renal carcinoma progression in the context of HIF dysregulation will be of particular interest." (PMID 30338240, 2018). "Our study suggests that blocking HIF-2α in (pVHL-defective) renal carcinoma induces CHCHD4 and promotes a metabolic profile that could be exploited therapeutically." (PMID 30338240, 2018). "We found that knockdown of HIF-2α in 786O cells caused elevated CHCHD4 and respiratory chain subunit expression and led to increased basal OCR, suggesting the possibility that HIF-dependent inhibition of mitochondrial function in pVHL mutated renal carcinoma involves CHCHD4." (PMID 30338240, 2018).
type 2 diabetes (2 papers, 2020 to 2023). "The region on Chr C2 near SNPs 5 and 6, contained four known genes (TRA2B, CHCHD4, IGF2BP2 and SENP2) but none of these genes contained disease-associated protein-coding changes, despite TRA2B and IGF2BP2 having association with type 2 diabetes in other species." (PMID 33228033, 2020).
clear cell renal cell carcinoma (1 paper, 2018). "Bioinformatics analyses of the Cancer Genome Atlas (TCGA-KIRC) data collection showed significantly increased CHCHD4 expression in clear cell renal cell carcinoma (ccRCC) designated as VHL non-mutated compared with those designated as VHL mutated in the collection." (PMID 30338240, 2018).
myocardial ischemia (1 paper, 2023). A disorder of cardiac function caused by insufficient blood flow to the muscle tissue of the heart. "We hypothesize that the elevated CHCHD4 protein in the ICM-HF group is a compensatory manifestation of mitochondrial damage due to hypoxia in cardiomyocytes caused by myocardial ischemia." (PMID 37008314, 2023).
osteosarcoma (1 paper, 2019). A usually aggressive malignant bone-forming mesenchymal neoplasm, predominantly affecting adolescents and young adults. "Similarly the mitochondrial IMS protein coiled-coil helix domain containing protein 4 (CHCHD4, Mia40 in yeast) has also been shown to stimulate mitochondrial perinuclear clustering, and thus intracellular oxygenation, in a HIF-1α-dependent manner in U2OS osteosarcoma cells." (PMID 30767037, 2019).
pulmonary arterial hypertension (1 paper, 2024). Pulmonary arterial hypertension (PAH) is a group of diseases characterized by mean pulmonary artery pressure >20 mmHg and elevated pulmonary arterial resistance leading to right heart failure. "A previous study has reported that CHCHD4 orchestrates mitochondrial OXPHOS and antagonizes the aberrant growth and migration of pulmonary artery smooth muscle cells in pulmonary arterial hypertension (PAH)." (PMID 38919950, 2024).
renal cell carcinoma (1 paper, 2022). "Furthermore, pVHL can promote the expression of CHCHD4 in renal cell carcinoma cells." (PMID 36482116, 2022).
tumor (14 papers, 2013 to 2025). "CHCHD4 overexpression was found in LUAD tumor tissues and cells, and high CHCHD4 was associated with a poor prognosis." (PMID 36482116, 2022). "Loss of CHCHD4 was shown to protect tumour cells from the growth inhibitory effects of CI inhibitors, whilst overexpression of CHCHD4 was shown to confer significant sensitivity to CI inhibitors, partly through increased mitochondrial ROS production." (PMID 33599699, 2021). "We found that CHCHD4 overexpression in human cancers correlates with the hypoxia gene signature and is associated with tumor progression and poor patient survival." (PMID 28497026, 2017). "Knockdown of CHCHD4 correlated with reduced tumor progression and was linked to the stability of HIF1A (hypoxia-inducible factor 1 alpha subunit), one of the central players of the HIF pathway response to hypoxia." (PMID 28701417, 2017). "By analysing the GEPIA database, we showed that CHCHD4 was overexpressed in LUAD tumor tissues and that the upregulated CHCHD4 was associated with poor prognosis of LUAD patients, suggesting that CHCHD4 may be a key oncogene in LUAD." (PMID 36482116, 2022). "We found that loss of CHCHD4 protects tumour cells from respiratory chain inhibition at CI, while elevated CHCHD4 expression in tumour cells leads to significantly increased sensitivity to CI inhibition, in part through the production of mitochondrial reactive oxygen species (ROS)." (PMID 30886710, 2019). "Knockdown of CHCHD4 was correlated with reduced tumor progression and was also linked to the stability of Hif1a, a critical component of the HIF pathway that responds to hypoxia; this was the first report of an association between the mitochondrial disulfide relay system and cancer." (PMID 27033519, 2016). "Research shows that CHCHD4 drives tumor cell growth, activates the mTORC1 signaling, and influences metabolism mediated by the respiratory chain and complex I biology." (PMID 39159158, 2024). "The results of the in vivo study verified that knockdown of CHCHD4 reduced tumour weight and volume." (PMID 36482116, 2022). "Recently, an increasing number of studies have shown that CHCHD4 is highly expressed in human cancers, and its increased expression is related to increased tumour progression, poor patient survival, and increased disease recurrence." (PMID 36482116, 2022). "Consistently, overexpression of CHCHD4 in tumour cells was shown to increase both CI-activity and mTORC1 activation, as well as affecting glutamine metabolism." (PMID 33599699, 2021). "Conversely, overexpression of CHCHD4 in tumour cells was shown to increase basal cellular OCR and intracellular hypoxia, and led to enhanced HIF-1α stabilisation in hypoxia, all of which were blocked by the CIV inhibitor sodium azide." (PMID 33599699, 2021). "Taken together, our data suggest that CHCHD4-mediated effects on the respiratory chain regulate both basal (normoxic) and adaptive (hypoxic) metabolic tumour cell responses and growth." (PMID 30886710, 2019). "We found that CHCHD4 (shRNA) knockdown led to significantly reduced tumour cell growth when cells were cultured in glucose-free (galactose-containing) media which forces them to utilise the respiratory chain and produce ATP via OXPHOS." (PMID 30886710, 2019). "Our study highlights an important role for CHCHD4 in regulating tumour cell metabolism and reveals that CHCHD4 confers metabolic vulnerabilities to tumour cells through its control of the mitochondrial respiratory chain and CI biology." (PMID 30886710, 2019). "Recently, we discovered that CHCHD4 regulates intracellular oxygenation in tumour cells, which is dependent on the functionally important cysteines of the CPC motif and CIV activity." (PMID 30886710, 2019). "It is highly possible that HIF transcriptionally dependent (negative) regulatory effects on mitochondrial function are negated in tumour cells expressing elevated CHCHD4 in normoxia due to CHCHD4's increased drive of mitochondrial function." (PMID 30886710, 2019).
tumor (continued). "In this study, using both loss- and gain-of-function approaches, we have further explored the mitochondrial mechanism(s) by which CHCHD4 regulates respiratory chain function and tumour cell metabolism." (PMID 30886710, 2019). "Overexpression of CHCHD4 in human cancers significantly correlates with the hypoxia gene signature, tumour progression, disease recurrence and poor patient survival." (PMID 30886710, 2019). "As our SILAC analyses demonstrated significant changes in the expression of respiratory chain subunits, next we assessed the effect of CHCHD4 expression on tumour cell metabolism and growth in normoxia and hypoxia." (PMID 30886710, 2019). "Tumour cells with elevated CHCHD4 expression and increased CI subunit expression and activity produced significant levels of mitochondrial ROS (superoxide) upon treatment with CI inhibitors." (PMID 30886710, 2019). "Overexpression of CHCHD4 in human cancers correlates with increased tumour progression and poor patient survival." (PMID 30886710, 2019). "Here, we show that elevated CHCHD4 expression provides a proliferative and metabolic advantage to tumour cells in normoxia and hypoxia." (PMID 30886710, 2019). "Collectively, our data indicate that CHCHD4 expression confers increased tumour cell sensitivity to mitochondrial ROS produced by CI inhibitors." (PMID 30886710, 2019). "Here, we have found that elevated CHCHD4 expression increases tumour cell growth rate and HIF-1α protein levels in normoxia and hypoxia." (PMID 30886710, 2019). "We have previously reported that overexpression of CHCHD4 in human cancers correlates with a hypoxia gene signature and increased tumour progression and metastasis, disease recurrence and poor patient survival." (PMID 30886710, 2019). "In this study, we evaluate the contribution of CHCHD4 mitochondrial function to HIF signaling in tumor cells." (PMID 28497026, 2017). "Taken together, our study indicates that CHCHD4 can control the distribution of the mitochondrial network in tumor cells through its role in regulating respiratory chain function, intracellular oxygenation, and HIF activation." (PMID 28497026, 2017). "Here, we show that either long-term (72 h) exposure to hypoxia (1% O2) or elevated expression of CHCHD4 in tumor cells in normoxia leads to perinuclear accumulation of mitochondria, which is dependent on the expression of HIF-1α." (PMID 28497026, 2017). "We show that increased expression of CHCHD4 in tumor cells leads to intracellular hypoxia and constitutive activation of HIF." (PMID 28497026, 2017). "Here, we found that increased expression of CHCHD4 in tumor cells resulted in perinuclear accumulation of the mitochondria, intracellular hypoxia associated with the perinuclear region and constitutive HIF activation in normoxia." (PMID 28497026, 2017). "Specifically, increasing evidence indicates that CHCHD4 play important roles in regulating mitochondrial respiratory chain, which in turn affects tumor proliferation and EMT-related phenotypes, cellular oxygen consumption rate and metabolism, as well as energy homeostasis." (PMID 37438854, 2023). "One explanation may be that, in tumours with up-regulated CHCHD4, increased proliferation leads to outgrowing of the vascular supply of oxygen, promoting hypoxia, a known driver of EMT phenotypes." (PMID 33599699, 2021). "CHCHD4 has been shown to negatively regulate the expression of genes related to EMT phenotypes, which seems contrary to the finding that increased CHCHD4 expression in tumours is associated with tumour progression in patients with certain cancer types." (PMID 33599699, 2021).
tumor (continued). "Furthermore, overexpression of CHCHD4 was shown to provide a proliferative advantage to tumour cells in both normoxia and hypoxia, proposedly due to CHCHD4 expression stimulating the most efficient utilisation of glucose depending on oxygen levels." (PMID 33599699, 2021). "However, mitochondrial ROS is involved in how CHCHD4 regulates tumour cell survival and growth, specifically in the context of CI inhibitors." (PMID 33599699, 2021). "Indeed, here and previously, we have shown that elevated expression of CHCHD4 in tumour cells increases hypoxic production of cellular lactate." (PMID 30886710, 2019). "However, our study also demonstrates that elevated CHCHD4 expression renders tumour cells more sensitive to growth inhibition by CI inhibitors, in part by increasing ROS production." (PMID 30886710, 2019). "Paradoxically, here we found that elevated CHCHD4 expression in tumour cells leads to significantly reduced levels of cellular lactate in normoxia and no significant change in PDK1 (data not shown), which is consistent with an increased respiratory drive in these cells." (PMID 30886710, 2019). "Thus, the increased sensitivity of CHCHD4 (WT)-expressing cells to CI inhibitors (rotenone) correlates with increased ROS production in these cells, suggesting that CHCHD4 expression levels determines tumour cell sensitivity to oxidative stress." (PMID 30886710, 2019). "Given this relationship between CHCHD4 and CI biology, we hypothesised that elevated expression of CHCHD4 in tumour cells may render them more sensitive to respiratory chain OXPHOS inhibitors." (PMID 30886710, 2019). "Furthermore, previously, we have discovered that elevated expression of CHCHD4 in tumor cells leads to increased OCR." (PMID 28497026, 2017). "We show that either long-term exposure of cells to hypoxia (72 h) or increased expression of CHCHD4 in tumor cells leads to (i) the redistribution of the mitochondria to the perinuclear region of the cell, (ii) HIF-1α stabilization, and (iii) the upregulation of HIF targets." (PMID 28497026, 2017). "Additionally, CHCHD4 knockdown suppressed the growth of xenograft tumours." (PMID 36482116, 2022). "Furthermore, CHCHD4 knockdown significantly reduced MYC expression in xenograft tumours." (PMID 36482116, 2022). "In addition, CHCHD4 knockdown suppressed xenograft tumour growth." (PMID 36482116, 2022). "Furthermore, knockdown of CHCHD4 inhibited the malignant phenotypes of LUAD cells and xenograft tumour growth, suggesting that CHCHD4 might be a key oncogene in LUAD." (PMID 36482116, 2022). "Indeed, shRNA knockdown of CHCHD4 has been shown to reduce tumour cell invasion in hypoxia." (PMID 33599699, 2021). "Therefore, CHCHD4 appears to regulate tumour cell proliferation, in part through its effects on CI-mediated metabolism, via a proposed mechanism whereby CHCHD4 influences amino acid stimulation of mTORC1-dependent protein synthesis, thus promoting tumour cell proliferation." (PMID 33599699, 2021). "Thus, CHCHD4 is primely positioned to influence tumour cell biology." (PMID 33599699, 2021). "Thus, CHCHD4 may also influence whole CI assembly and activity in tumour cells via other proteins involved in DRS function independently of its ability to import CI accessory subunits." (PMID 30886710, 2019). "Through its central role in controlling ETC function via the DRS, CHCHD4 has been shown to regulate basal cellular OCR, intracellular oxygenation and hypoxia signalling in tumour cells." (PMID 33599699, 2021). "Consistently, shRNA knockdown of CHCHD4 was shown to significantly block HIF-1α stabilisation and HIF target gene expression in tumour cells in response to hypoxia, and block tumour growth and angiogenesis in vivo." (PMID 33599699, 2021). "Previously, we have shown that CHCHD4 regulates HIF-1α protein induction and HIF signalling in hypoxia and is required for tumour growth in vivo." (PMID 30886710, 2019).